DDR1 (discoidin domain receptor tyrosine kinase 1)
Diseases named in the same sentence as DDR1 in open-access papers (continued):
Sharing a sentence is not in itself a finding about the gene and the disease.
cancer (continued). "However previous studies have demonstrated a positive association between DDR1 protein expression and poor prognosis in solid tumors, thus supporting the hypothesis that DDR1 expression enhances the aggressiveness of malignant tumors." (PMID 28143619, 2017). "In addition, these data suggest that this DDR1-IGF-IR functional cross-talk may play a role in cancer progression thereby establishing DDR1 as an important novel therapeutic target in cancers associated with a dysregulated IGF-IR pathway." (PMID 25840417, 2015). "By stabilizing cell surface E-cadherin, DDR1 enhances intercellular adhesion and facilitates the aggregation of cancer cells." (PMID 40563472, 2025). "Further analysis of the correlation between DDR1 expression and the GC stage revealed that aberrant DDR1 expression occurred during early cancer development (right)." (PMID 40456688, 2025). "The online analysis conducted using the GSCA database reveals a robust inverse relationship between DDR1 expression and key immunomodulatory markers across several cancer types, notably IBC (BRCA in TCGA), LUSC, and PAAD (highlighted by black boxes)." (PMID 40869052, 2025). "DDR1 is frequently overexpressed in various types of cancers, including gastric, breast, lung, brain, liver, esophageal cancer, and leukemia." (PMID 40456688, 2025). "DDR1 has been extensively studied for its tumorigenic and metastatic characteristics in human cancers, including HCC." (PMID 40458187, 2025). "In a noteworthy observation, DDR1, a gene previously reported to be involved with metastasis in various types of cancer, was discovered to be significantly upregulated." (PMID 40458187, 2025). "DDR1 was consistently overexpressed in 21 cancer types, correlating with poor prognosis and reduced immune cell infiltration." (PMID 40869052, 2025). "In the current study, we observed that DDR1 overexpression activated the AKT and YAP-TEAD signaling axis, which drove the oncogenic transcription program associated with an increase in cancer cell proliferation." (PMID 40456688, 2025). "Compared to hetero-trimers, COL1 homo-trimers in cancer cells strongly induce phosphorylation of DDR1, FAK, AKT, and ERK." (PMID 40721833, 2025). "Our comprehensive pan-cancer analysis demonstrates that DDR1 is markedly overexpressed in diverse malignancies and is strongly associated with poor clinical outcomes, immunotherapy resistance, and diminished antitumor immune cell infiltration." (PMID 40869052, 2025). "DDR1 has also recently gained attention as a potential therapeutic target due to its ability to promote therapy resistance in several cancer types." (PMID 40401507, 2025). "To further investigate DDR1 expression patterns across cancers, we integrated data from three independent sources: GEPIA 2.0, KM-Plotter, and TIMER 2.0." (PMID 40869052, 2025). "Recent research highlights the significance of DDR1 in cancer, though its precise role in cancer progression is still debated." (PMID 40456688, 2025). "Overexpression of wild-type DDR1 is commonly observed in various cancers, indicating that it represents the primary oncogenic alteration of DDR1." (PMID 40456688, 2025). "DDR1 plays a pivotal role in mediating the adhesion of cancer cells to their microenvironment, a critical factor in cell invasion and metastasis." (PMID 40563472, 2025). "TM4SF1, a member of the transmembrane 4 superfamily, is known to facilitate cell motility and adhesion and has been implicated in the promotion of epithelial–mesenchymal transition (EMT), potentially enhancing DDR1’s pro-invasive function in cancer." (PMID 40869052, 2025).
cancer (continued). "As a collagen receptor, DDR1 plays a crucial cellular role in detecting collagen signalling in the surrounding environment, and its expression is dysregulated in various cancers." (PMID 40105492, 2025). "For example, two selective DDR1 inhibitors, 7rh and 7rj, exhibited potent anti-proliferative effects and strong suppression of invasion, adhesion, and tumorigenicity in cancer cells expressing high levels of DDR1." (PMID 40456688, 2025). "As one major ECM receptor, DDR1 pathway played a crucial role in immune regulation, progression, metastasis and carcinogenesis in various types of cancer." (PMID 38388466, 2024). "Discoidin domain receptor 1 (DDR1) kinase has emerged as a promising target for cancer therapy, and selective DDR1 inhibitors have shown promise as effective therapeutic candidates." (PMID 38675389, 2024). "Upon decellularization, cancer cells were seeded on these matrices and analyzed for DDR1 expression." (PMID 38907027, 2024). "Collectively, these results suggest that the lactate-sustained P4HA1/DDR1 axis contributes to the cancer cell colonization and the formation of metastasis in vivo." (PMID 38907027, 2024). "DDR1 is a receptor tyrosine kinase that reportedly functions in development and progression of several cancer types." (PMID 38177123, 2024). "In line with our conclusion, previous studies proposed that DDR1 enhanced the ability to migrate and invade in various cancers." (PMID 39567474, 2024). "And in this step, DDR1 was also revealed to play a role in the degradation of extracellular matrix through upregulation of MMP2 that facilitates cancer cell invasion." (PMID 37271822, 2023). "To better understand DDR1 expression levels in various cancer types, we first performed a pan-cancer analysis of 33 cancers in the TCGA database." (PMID 37031216, 2023). "Our results showed that DDR1 was dysregulated in 17 types of cancer, which was consistent with previous studies." (PMID 37031216, 2023). "The results illustrated that CTLA4 and ICOS were negatively correlated with DDR1 among 19 cancers while positively correlated with DDR1 in LAML and LIHC." (PMID 37031216, 2023). "Our data showed that DDR1 expression was positively correlated with the sensitivity to the following drugs in most cancers; AR-42, I-BET-762, TG101348, JW-7-24-1, TPCA-1, vorinostat, methotrexate, TL-1-85, BX-912, and NPK76-II-72-1." (PMID 37031216, 2023). "The results showed that DDR1 was closely related to angiogenesis, DNA damage, hypoxia, stemness, and metastasis at the single-cell level in most cancers." (PMID 37031216, 2023). "Low DDR1 expression has corresponded with poor DSS in 8 types of cancer, including BLCA, ESCA, KICH, KIRC, KIRP, LUSC, MESO, and UVM." (PMID 37031216, 2023). "Last, the current study was conducted mostly based on bioinformatic analysis and in vitro studies; further analysis of clinical samples from cancer patients are necessary to confirm the aberrant expression of DDR1." (PMID 37031216, 2023). "We propose that low DDR1 coupled to moderate levels of β1 integrins provide the required degree of adhesion to collagen for cancer amoeboid 3D migration." (PMID 37217519, 2023). "Next, we performed the prognostic value of DDR1 expression in pan-cancer, including OS, DSS, DFI, and PFI analyses based on the TCGA database." (PMID 37031216, 2023). "We used a range of bioinformatics approaches to explore the potential carcinogenic role of DDR1 in multiple cancers." (PMID 37031216, 2023). "Our results showed that the expression of DDR1 was highly different in 25 of the 26 cancers versus normal tissues when the TCGA and GTEx databases were combined." (PMID 37031216, 2023). "When the intensity of DDR1 expression in carcinoma was correlated with clinicopathological parameters, it was significantly associated with stage D in the modified Dukes’ staging system (P = 0.013)." (PMID 37271822, 2023).
cancer (continued). "Comparison between the 3 studied groups showed a stepwise increase of H-score of DDR1 expression from adjacent normal (mean ± SD = 20 ± 8.9) to the carcinoma group (137.4 ± 96.9)." (PMID 37271822, 2023). "It revealed a stepwise increase of DDR1 expression among studied groups toward carcinoma (P = 0.006)." (PMID 37271822, 2023). "DDR1 promoted collective cancer-cell migration through DDR1–Par3/Par6 complex independent of its kinase activity or collagen binding." (PMID 35140331, 2022). "Prognostic analysis conducted by PrognoScan, Kaplan–Meier plotter, and GEPIA databases also suggested that DDR1 affected the prognosis of patients with various types of cancer to varying degrees." (PMID 35935941, 2022). "DDR1 has emerged as an important contributor and a therapeutic target in cancer growth and metastasis." (PMID 35309920, 2022). "Consistently, the gene expression of collagen I receptors, linked to active tissue remodeling and cancer, including DDR2, ITGA2, ITGA10, ITGA11 and ITGB1 was higher in OS compared to RMS, whilst DDR1 expression was higher in RMS tumors." (PMID 35957513, 2022). "On the basis of individual cancer stages, DDR1 expressions of STAD were markedly higher in stages 1–4." (PMID 35935941, 2022). "Utilizing the patient datasets from Pan-Cancer (c-Bioportal), we observed a significant positive correlation between DDR1 expression and expression of genes BCR, EGFR, and ERBB2." (PMID 35664781, 2022). "DDR1 was identified as a neurotrophic receptor tyrosine kinase (NTRK4) highly upregulated in cancers and is documented to have therapeutic value in GBM." (PMID 35664781, 2022). "The receptor tyrosine kinase DDR1 has been shown to be vitally important in the proliferation, migration, and metastasis of cancer cells." (PMID 35626066, 2022). "We then asked if DDR1-induced TAN infiltration directly enhanced the metastatic capability of cancer cells." (PMID 34237033, 2021). "To investigate the influence of cancer cell DDR1 signaling on the TME, we screened for cancer cell DDR1-induced cytokine production using a human chemokine antibody array." (PMID 34237033, 2021). "In particular, Trametinib-treated cancer cells showed de novo enhancer formation near the DDR1 gene that were enriched for BRD4 (bromodomain-containing protein 4) binding, which promoted a drastic increase in DDR1 expression." (PMID 34461089, 2021). "Murine Kupffer cells have also been shown to express DDR1, and pre-treatment of these cells with collagen led to an increased ability to attract cancer cells in a DDR1-dependent manner." (PMID 34956223, 2021). "DDR1 has been shown to play a critical role in promoting the proliferation of several cancer cells, in vitro and in vivo." (PMID 33917302, 2021). "The dependence upon DDR1 is demonstrated by the fact that CCM from DDR1-expressing cancer cell/collagen I cultures stimulates NE activity in neutrophils, but NE activity is significantly reduced after exposure to CCM from DDR1-knockdown clones." (PMID 34237033, 2021). "DDR1 amplification is commonly observed in various cancers and is significantly deregulated in aggressive cancers." (PMID 34237033, 2021). "In contrast, the reexpression of DDR1 recovered the effect of neutrophil-mediated cancer cell invasion in MDA-PATC 148KD#32-exDDR1 and BxPC-3KD#32-exDDR1 cells." (PMID 34237033, 2021). "DDR1 responds to collagen I, resulting in strengthened survival, proliferation, and stemness in cancer cells, and promoting metastatic colonization in liver." (PMID 33976105, 2021). "In conclusion, our results reveal that ECM remodeling activates the overexpressed extracellular matrix collagen receptor DDR1 promoting colonization phenotypes (e.g., survival, outgrowth and stemness of cancer cells in the metastatic site)." (PMID 33976105, 2021). "More importantly, targeting cancer cells by pharmacological inactivation of DDR1 or targeting microenvironmental TGF-β1-collagen I loop exhibited a prominent anti-metastasis effect in mice." (PMID 33976105, 2021).
cancer (continued). "The results demonstrate that the activation of cancer cell DDR1 by collagen is an essential step for TAN infiltration and NET formation." (PMID 34237033, 2021). "Together, these results suggest that DDR1 on cancer cells drives CXCL5 production, CD45+CD11b+Ly6G+ TAN infiltration, and liver metastasis." (PMID 34237033, 2021). "DDR1 is predominantly expressed in epithelial cells and is reported to be involved in the progression of cancer." (PMID 33828969, 2021). "We then repeated the cancer cell invasion assay experiment using NCCM in the presence or absence of collagen I. NCCM from MDA-PATC 148CTL/collagen I/neutrophil cultures induced cancer cell invasion in a DDR1-independent manner." (PMID 34237033, 2021). "Further in vivo analysis of cancer development during treatment using specific DDR1 or DDR2 inhibitors, such as 7rh, 2.45, or WRG-28, in different cancers are needed." (PMID 33917302, 2021). "Because cellular survival is a critical prerequisite for colonization when cancer cells are disseminated into host organs, the pro-survival role of DDR1 in UM cells was examined." (PMID 33976105, 2021). "Knocking down DDR1 in the cancer cells significantly reduced neutrophil-mediated cancer cell invasion." (PMID 34237033, 2021). "Activation of DDR1 contributes to tumorgenicity in PDAC and selective, DDR1-specific kinase inhibitors can decrease cancer cell proliferation, invasion, and adhesion across several cancer models." (PMID 33233470, 2020). "How DDRs induce cancer signaling is another critical question, although we established an important connection between DDR1 signaling and the β-catenin pathway." (PMID 32117772, 2020). "Beyond normal human physiology, increased DDR1 expression has been reported in fibrotic disease and cancer." (PMID 33233470, 2020). "Dapagliflozin treatment also significantly reduced Y792 tyrosine phosphorylation of DDR1 leading to decrement of DDR1 function and detachment of cancer cells." (PMID 31979355, 2020). "Aberrant expression of DDR1 has been detected in several human cancers including ovarian, breast, gastric and lung cancers, and is often associated with increased invasiveness." (PMID 32668815, 2020). "The elevated expression of DDR1 in fast-growing invasive tumors and associated metastases has dramatically increased the researcher ́s attention in the pathological implication of DDR1 in cancer." (PMID 32090682, 2020). "In fact, in cancer of other organs such as lung, breast, colon, and prostate, DDR1 is already considered as a therapeutic target." (PMID 33173221, 2020). "On the other hand, many studies have shown that overexpression of DDR1 in several cancer types correlates with disease progression." (PMID 33014862, 2020). "Even if several membrane proteins can be targeted by this approach, three examples will be described in this section: Neu-1, DDR1, and GPCRs which are involved in several cancer processes." (PMID 32351895, 2020). "The expression of DDR1 in several different types of human cancer including human esophageal, gastric cancer, glioma, breast cancer, lung cancer, suggests a function in tumor progression." (PMID 32351895, 2020). "Discoidin domain receptor-1 (DDR1) tyrosine kinase is highly expressed in a variety of human cancers and involved in various steps of tumorigenesis." (PMID 31253192, 2019). "Selective inhibitors of DDR1 are being developed and show efficacy in preclinical models of fibrosis and cancer." (PMID 31717573, 2019). "Increased DDR1 expression has been reported and functions as an onco-protein in many types of cancer." (PMID 31253192, 2019). "The overexpression of DDR1 has been reported in a number of cancer types, including breast and lung cancers, and is often associated with more migratory and invasive phenotypes." (PMID 31717573, 2019).
cancer (continued). "DDR1 pharmacological inhibition reduces lung tumour progression in mouse and patient‐derived xenograft models, suggesting an important kinase‐dependent function of DDR1 in this cancer." (PMID 29438985, 2018). "The activations of collagen-mediated DDRs are characterized by slow, sustained activity, and the up-regulation of DDR1 expression has been detected in several cancer types, including brain, esophageal, ovarian, and breast cancer." (PMID 29559654, 2018). "We also identified a potentially important mechanism by which DDR1 TK activity promotes cancer cell invasion and metastasis formation." (PMID 29438985, 2018). "As a signaling mediator, DDR1 regulates diverse downstream effectors which confer the aggressive behaviors of DDR1 in different cancers." (PMID 28743276, 2017). "Known tyrosine kinase inhibitors (dasatinib, imatinib, nilotinib) initially identified as blockers of the tyrosine kinase BCR-ABL for potential use in cancer, display also the ability to block collagen-mediated DDR1 autophosphorylation." (PMID 28536691, 2017). "Discoidin Domain Receptor 1 (DDR1), a subfamily of receptor tyrosine kinases (RTKs), is critical for cancer cell adhesion, proliferation and differentiation, cell migration and invasion." (PMID 28368050, 2017). "The pro-survival effect of DDR1 in cancer cells also suggested its potential as a therapeutic target." (PMID 28143619, 2017). "Discoidin Domain Receptor 1 (DDR1) belongs to the family of collagen receptor tyrosine kinases that confers the progression of various cancers." (PMID 28743276, 2017). "DDR1 is often overexpressed in cancer, and plays a critical role in cancer cell migration, EMT, and metastases." (PMID 28591735, 2017). "Along these lines, although DDR1 enhances migration of various cancer cells by increasing adhesion to collagen, it does not always promote cell adhesion." (PMID 27391444, 2016). "In particular, we show a complex functional cooperation involving IGF-IR, GPER and DDR1 through which IGF-I up-regulates first the expression of COL1A1 and certain DDR1 target genes, thereafter stimulating cancer cell motility and chemotactic response." (PMID 27384677, 2016). "While activation of DDRs is required for normal development, studies have reported differential expression and mutations of DDR1 and DDR2 in several cancers." (PMID 27014069, 2016). "Discoidin Domain Receptor 1 (DDR1) is a collagen receptor tyrosine-kinase that contributes to epithelial-to-mesenchymal transition and enhances cancer progression." (PMID 26655502, 2016). "Nilotinib binds to and inhibits the kinase domain of ABL/BCR-ABL but also interacts with other cancer-expressed kinases including DDR1, KIT and PDGFR." (PMID 27556570, 2016). "The DDR1-ERK signaling cascade is required for the functions of both cancer cells and endothelial cells." (PMID 25992553, 2015). "Accumulated evidence indicates that DDR1 is overexpressed in invasive tumors including breast, prostate, lung and cancer cells overexpressing DDR1 display increased migration and invasion." (PMID 25978031, 2015). "The discoidin domain receptor-1 (DDR1) is a collagen tyrosine kinase over-expressed in several human cancers." (PMID 24839982, 2014). "We report the inhibition of these unusual receptor tyrosine kinases by the multi-targeted cancer drugs imatinib and ponatinib, as well as the selective type II inhibitor DDR1-IN-1." (PMID 24768818, 2014). "Knockdown of DDR1 expression induced apoptosis in lung tumor cells and a dramatic reduction in bone metastasis, thus increasing survival rates in animal models of cancer." (PMID 25369402, 2014).